IL1B (interleukin 1 beta)
Diseases named in the same sentence as IL1B in open-access papers (continued):
Sharing a sentence is not in itself a finding about the gene and the disease.
Tinnitus (continued). "However, no study on the effect of IL-1β antagonists on tinnitus has been performed yet, either in animals or in humans." (PMID 35207270, 2022). "While our panels did not include proteins such as IL-1β or BDNF, our analysis suggest that IL-10 plays no role in constant tinnitus." (PMID 38079022, 2023).
toxoplasmosis (11 papers, 2015 to 2024). A parasitic disease contracted by the ingestion or fetal transmission of toxoplasma gondii. "Our aim was to analyze the associations between the serum levels of IL-33 and IL-1β in IUGR and toxoplasmosis during pregnancy." (PMID 39065188, 2024). "Because NLRP3-dependent production of IL-1β and nitric oxide (NO) in Toxoplasma-infected human cells is involved in the GRA15-dependent virulence mechanism, blocking NO or IL-1β production in the host could represent a novel therapeutic approach for treating human toxoplasmosis." (PMID 30301855, 2018). "It was also observed that pregnant women in the acute phase of toxoplasmosis (IgM+/IgG-) presented higher levels of TNF, IL-1β, IL-2, and IL-12." (PMID 36742306, 2023). "Our results are consistent with those of previous studies, that is, T. gondii triggers NLRP3 or NLRP1, which leads to parasite restriction and resistance to toxoplasmosis, and p38 MAPK is important for the regulation of NLRP1 or NLRP3 inflammasome activation and IL-1β secretion." (PMID 33712075, 2021). "It is possible that type II GRA15-dependent IL-1β production, which suppresses the IFN-γ-induced IDO1-dependent immune response via iNOS, might be involved in the pathogenesis of human toxoplasmosis." (PMID 30301855, 2018). "Because IL1β can enhance the IL12-mediated stimulation of IFNγ production and CD40–CD40L interaction can activate Toxoplasma destruction through autophagy, it is likely that GRA15 plays a role in human toxoplasmosis." (PMID 28278184, 2017). "Since IL-1β is expressed in the intestine following T. gondii infection, and there are TLR ligands produced by the parasite or by commensal bacteria, it is possible that these signals contribute to the group 3 ILC CD80 expression seen during toxoplasmosis." (PMID 26010337, 2015).
urinary tract infection (11 papers, 2007 to 2025). "The NLRP3 inflammasome and IL-1β have recently been linked to the severity of uropathogenic Escherichia coli (UPEC)-mediated urinary tract infection (UTI)." (PMID 33318544, 2020). "And IL-1β is also a potent pro-inflammatory cytokine amplifying innate immune responses in several infectious diseases including urinary tract infections." (PMID 41042739, 2025). "The inflammasome-associated proteins caspase-1, caspase-4 and NLRP3 have been emphasised to be essential in the host cell response during urinary tract infection (UTI) by regulating IL-1β release." (PMID 35132157, 2022). "The inflammasome-associated proteins caspase-1, caspase-4 and NLRP3 have been emphasised to be vital in the host response during urinary tract infection by regulating IL-1β release." (PMID 35132157, 2022). "The NLRP3 inflammasome and IL-1β release have recently been suggested to be important for the progression of urinary tract infection (UTI)." (PMID 29662840, 2018). "IL-6 and IL-1β have been found to be increased in inflammatory urinary tract disease, indicating that IL-6 may also play an essential role in bladder dysfunction related to urinary tract infection." (PMID 29204439, 2017). "Interestingly, while the pH of our urine samples were within neutral range suggesting the absence of urinary tract infections and normal renal function, two samples in our study, 3119–2 and 3119–13, displayed unusually elevated urinary IL-1β levels." (PMID 25403235, 2014).
Abdominal obesity (10 papers, 2018 to 2024). Excessive fat around the stomach and abdomen. "Among obese adolescent girls aged 13–18 years old, a significantly higher concentration of IL-1β was found in the group with central obesity (WHR > 0.8), along with a positive correlation between WHR and IL-1β." (PMID 38257150, 2024). "Likewise, serum levels of IL-1β and FFAs appear to be more related to abdominal obesity than to the metabolic state." (PMID 31272370, 2019). "Weight, abdominal obesity, triglycerides, and plasma ghrelin were inversely correlated with greater adherence to MDP with p < 0.01 and height, HbA1c, plasma IL-1β, and XOD levels, ROS production in PBMCs by LPS, and urine MDA with p < 0.05." (PMID 35624765, 2022). "The result showed that central obesity lowers adiponectin plasma levels via increasing proinflammatory adipokines, such as TNF-alpha, leptin, and IL-1β." (PMID 33946540, 2021). "Individuals with abdominal obesity often exhibit high levels ofproinflammatory cytokines (tumor necrosis factor-α (TNF-α), interleukin-1α (IL-1α), interleukin-1β (IL-1β), interleukin-6 (IL-6)and interleukin-8 (IL-8)), which can be considered significant prognostic indicators of CVD risk." (PMID 39076338, 2024). "Serum concentration of IL-1β, FFAs, and mRNA expression levels of TLR2, MyD88, and NFĸB may be resulted from abdominal obesity and not be related to the presence or absence of metabolic health." (PMID 31272370, 2019).
age-related macular degeneration (10 papers, 2012 to 2023). Age-related loss of vision in the central portion of the retina (macula), secondary to retinal degeneration. "A recent study of age-related macular degeneration (AMD) reported that IL-17A induces IL-1β secretion from retinal pigment epithelium (RPE) cells via NLRP3 inflammasome activation." (PMID 37109536, 2023). "Studies focusing on age-related macular degeneration have also reported NLRP3-inflammasomes-dependent cytokine induction of IL-1β and IL-18, both locally and systemically." (PMID 34071438, 2021). "Previous studies have suggested IL-1β plays an important role in inducing photoreceptor apoptosis, using models of retinopathy of prematurity and age-related macular degeneration." (PMID 32714489, 2020). "Increased expression of IL-1β and IL-18 is found in age-related macular degeneration (AMD), diabetic retinopathy, retinitis pigmentosa, and glaucoma." (PMID 35008812, 2021). "In patients with age-related macular degeneration (AMD), increased mRNA levels of NLRP3, IL-1β, and pro-IL-18 in lesions of the retinal pigment epithelium and photoreceptors were detected." (PMID 28273882, 2017).
aortic aneurysm (10 papers, 2011 to 2026). A ruptured aneurysm located in the wall of the proximal portion of the descending aorta proceeding from the arch of the aorta. "This review discusses the mechanisms by which IL-1β promotes aortic aneurysm inflammation and the principles underlying the alleviation of aortic aneurysm immunopathology." (PMID 42292365, 2026). "Current research indicates that inhibiting IL-1β activity and expression can alleviate aortic aneurysms." (PMID 42292365, 2026). "IL-1β contributes to aortic aneurysm inflammation by recruiting immune cells to the vascular wall, enhancing matrix metalloproteinase activation, and inducing apoptosis and phenotypic transformation of vascular smooth muscle cells." (PMID 42292365, 2026). "In this context, recent studies reported that the inhibition of cytokine IL-1β attenuates experimental development of aortic aneurysm, as well as activation of TGF-β signalling." (PMID 26539497, 2015). "Furthermore, BMSCs have been established to significantly attenuate aortic elastin degradation and aortic aneurysm development as well as reduce IL-1β." (PMID 33460398, 2021). "Notably, local IL-1β might participate in the formation of aortic dissecting aneurysms by promoting extracellular matrix (ECM) metalloproteinase (MMP)-2 and MMP-9 and the breakage of elastin fibers, thus weakening the biomechanical properties of the aortic wall." (PMID 33460398, 2021). "Indeed, a significant relationship between the pathogenesis of AAA and serum IL-1β and CCL5 levels has been reported, indicating that aortic aneurysm formation and progression could be blocked by genetic or pharmacological inhibition of IL-1β or CCL5." (PMID 37205167, 2022).
autism spectrum disorder (10 papers, 2012 to 2025). A spectrum of developmental disorders that includes autism, and Asperger syndrome. "As an example, IL-1β and IL-6 has been found increased in maternal serum, amniotic fluid, and serum of children subsequently diagnosed with autism spectrum disorders (ASD) as well as in the well-known maternal immune activation rodent model." (PMID 38052845, 2023). "Some patients with autism spectrum disorders (ASDs) have an augmented level of proinflammatory cytokines IL-12, IL-6 and IL-1β, while IFNγ and the anti-inflammatory cytokine IL-10 seem to be reduced." (PMID 36835652, 2023). "In another meta-analysis patients with an autism spectrum disorder were reported to have increased blood concentrations of IL-1β, IL-6, IFN-ɣ and TNF-α." (PMID 34589729, 2021). "Samples from the brain and cerebrospinal fluid of patients with autism spectrum disorders show increased contents of inflammatory molecules, such as IL-1β, IL-6, TNF-α, MCP-1, and CXCL8/IL-8." (PMID 33506033, 2021). "Changes in monocyte cytokine production with toll like receptor (TLR) agonists in subjects with autism spectrum disorders (ASD) were best reflected by the IL-1β/IL-10 ratios in our previous research." (PMID 31554204, 2019). "Similar to the plasma from persons with DS, the blood from persons with autism spectrum disorder (ASD) contains increased amounts of EVs, and these can stimulate microglia in vitro to produce increased levels of IL-1β, thus propagating a pro-inflammatory profile." (PMID 34501378, 2021).
autoimmune thyroid disease (10 papers, 2011 to 2025). Inflammatory disease of the thyroid gland due to autoimmune responses leading to lymphocytic infiltration of the gland. "Other studies have shown that IL-1β can cause damage or apoptosis of thyroid follicular cells and promote the onset of autoimmune thyroiditis." (PMID 39712509, 2024). "For instance, IL1B was involved in mismatch repair, PTGS2 participated in the IL-17 signaling pathway and TNF signaling pathway, SELL was associated with autoimmune thyroid disease, and notably, all three genes were related to tyrosine metabolism." (PMID 40857330, 2025). "IL-1β is involved in autoimmune thyroiditis by inducing intercellular adhesion molecule-1 on thyroid follicular cells and interfering with the integrity of thyroid epithelium." (PMID 39712509, 2024). "Th17 cells enhance differentiation and proliferation by IL-1β stimulation, which was higher in autoimmune thyroid disease patients." (PMID 35457278, 2022). "Accordingly, the aim of this study was to define the relationship of IL-1β +3954 C/T (rs1143634), NLRP3 (rs3806265) T/C, and COX-2 (rs2745557) G/A gene polymorphisms susceptible to autoimmune thyroiditis development." (PMID 34790822, 2021). "IL-1β was also involved in the pathogenesis of autoimmune thyroid disease." (PMID 35457278, 2022). "Moreover, these Tregs had a significantly higher ability to maintain Foxp3 expression when activated in the presence of IL-1β, which enhanced their capacity to suppress the effector T cell response in vitro and ongoing experimental autoimmune thyroiditis in vivo." (PMID 33643294, 2020). "Therefore, IL1B may play a role in the pathogenesis of thyroid autoimmunity." (PMID 24465880, 2014). "Correlation between NLRP3, NLRP1, NLRC4, absent in melanoma 2 (AIM2), ASC, caspase-1, IL-1β, and IL-18 expression in the autoimmune thyroiditis group." (PMID 29915579, 2018).
bronchopulmonary dysplasia (10 papers, 2010 to 2025). Bronchopulmonary dysplasia is a chronic respiratory disease that results from complications related to lung injury during the treatment of infant acute respiratory distress syndrome in low-birth-weight premature infants or from abnormal lung development in older infants. "A study of extremely low-birth-weight children found bronchopulmonary dysplasia or death to be associated with higher concentrations of IL-1β, -6, -8, -10 and IFN-γ and lower concentrations of IL-17." (PMID 24714360, 2014). "IL-1β has been implicated in human neonatal lung injury and in bronchopulmonary dysplasia (BPD)." (PMID 38100545, 2023). "Exposure to or infusion of IL-1β and TNF-α caused the defects associated with peripartum intrauterine inflammation, abnormal lung development associated with bronchopulmonary dysplasia, and brain injury." (PMID 37099541, 2023). "Very low birth weight infants have increased concentrations of the proinflammatory cytokines IL-8, IL-1β, IL-6 and MCP-1 in tracheal aspirates and their levels were associated with the risk of bronchopulmonary dysplasia." (PMID 35725416, 2022). "Like preterm sheep, ventilated very low birth weight (VLBW) infants have increased concentrations of the pro-inflammatory cytokines IL-8, IL-1β, IL-6, and MCP-1 in tracheal aspirates and these increased levels correlate with an increased risk of bronchopulmonary dysplasia (BPD)." (PMID 21034485, 2010). "Bronchopulmonary dysplasia (BPD), a frequent complication in preterm infants receiving supplemental oxygen, is characterized by hyper-activation of macrophage inflammasomes, exuberant release of pro-inflammatory cytokines such as interleukin-1β (IL-1β), and Gasdermin D (GSDMD)-driven pyroptosis." (PMID 41345109, 2025). "IL1β is a well-known major modulator in IAI and bronchopulmonary dysplasia." (PMID 38481391, 2023).
chronic myeloid leukemia (10 papers, 2014 to 2025). "Moreover, our analysis revealed that SOCS2 levels are significantly increased in patients with acute and chronic myeloid leukemia, two hematological malignancies where disease progression is closely linked to IL-1β." (PMID 31775389, 2019). "Similar results were also observed in chronic myeloid leukemia (CML) patients in which genotyping demonstrated that genetic polymorphisms of IL-1β-rs16944, IL-18-rs1946518, and CARD8-rs2043211 were associated with the pathophysiological characteristics and treatment of CML patients." (PMID 30447690, 2018). "Such a dysregulation of IL-1Ra may also happen in other diseases involving IL-1β, such as chronic myelogenous leukaemia and hairy cell leukaemia." (PMID 25167060, 2014). "In chronic myeloid leukemia (CML), overexpression of the NLRP1 inflammasome significantly increased the IL-1β levels and inhibited apoptosis." (PMID 35897704, 2022).
coagulopathy (10 papers, 2011 to 2025). "IL-1β and the inflammasome may play some role in this process, as mice deficient in caspase-1 have shown reduced markers of coagulopathy and inflammation after STm infection." (PMID 40064845, 2025). "In addition, IL-1β is associated with different clinical manifestations, such as coagulopathy and thrombocytopenia." (PMID 35173184, 2022). "Proinflammatory cytokines, such as IL-6, IL1-β and TNF, are believed to cause the majority of symptoms, such as fever, malaise, and coagulopathies associated with infections." (PMID 21461372, 2011). "TF level was also positively correlated with TNF-α, IL-1β, IL-6, and MPO levels and was negatively correlated with IL-10, indicating that the TF level was closely associated with the inflammatory factors, which may cause coagulation disorders." (PMID 32587471, 2020). "Further data analysis and interpretation suggested the involvement of acute activation of TGFβ1, IL1β, and ADORA2A signaling, as well as the increased levels of fibrinogens and fibronectin to block coagulopathies." (PMID 33668155, 2021).
corneal disease (10 papers, 2009 to 2025). "To determine if IL-1β regulates corneal disease severity caused by MRSA, we injected 1×103 log phase the common MRSA isolate USA300 directly into the corneal stroma of IL-1α−/−, IL-1β−/−, and IL-1α/β−/− mice." (PMID 41415470, 2025). "We show here that Hla from strain USA300 is required to induce IL-1β secretion by neutrophils and to cause severe corneal disease in mice." (PMID 41415470, 2025). "We also found that corneal disease severity, neutrophil recruitment, and IL-1β secretion in infected corneas are dependent on Hla production, and that IL-1β secretion by neutrophils in vitro is dependent on Hla activation of the NLRP3 inflammasome." (PMID 41415470, 2025). "On the other hand, NF-κB plays an important role in IL-1β-related inflammatory diseases, including various corneal diseases." (PMID 20208988, 2010). "Effects of MIP-2 or IL-1β polyclonal antibody on the corneal diseases were observed by slit-lamp microscopy, histopathology, and ELISA." (PMID 19590756, 2009). "When mice received injections with anti-IL-1β polyclonal antibody, the severity of corneal disease was significantly reduced, and this was accompanied by a reduction in corneal PMN cells, bacterial load, and MIP-2 mRNA and protein expression." (PMID 19590756, 2009). "In this study, IL-1β was the proinflammatory cytokine with the highest expression levels in A. fumigatus and C. albicans keratitis, and the IL-1β expression levels were related closely to corneal disease severity and inflammatory cell infiltration." (PMID 19590756, 2009). "The ADAM10 inhibitor GI254023X blocked neutrophil IL-1β secretion induced by Hla-expressing CC8, but not by CC5 conditioned media, indicating that these Hla polymorphisms play an important role in Hla receptor binding and neutrophil IL-1β secretion, and affect corneal disease severity." (PMID 41415470, 2025). "IL-1β is also present in the tear fluid of individuals with corneal diseases." (PMID 22219637, 2011). "In other corneal diseases, including DED and alkali burn injury, NLRP3 activation has been shown to drive inflammation through IL-1β and IL-18 production." (PMID 40943162, 2025). "Clinical isolates that did not secrete Hla did not induce neutrophil IL-1β secretion and most did not induce corneal disease, behaving similarly to an α-hemolysin mutant (ΔHla)." (PMID 41415470, 2025). "In the current study, we demonstrate that Hla is important in neutrophil secretion of IL-1β following assembly of the NLRP3 inflammasome, and that neutrophil derived IL-1β plays an important role in a murine model of MRSA keratitis where it regulates corneal disease severity and bacterial killing." (PMID 41415470, 2025). "In this study, we evaluated the cytokine profiles of IL-2, IFN-γ, ICAM-1, IL-5, IL-6, IL-8, IL-10, IL-1β, MCP-1, IL-17A, IP-10, G-CSF, and VEGF-A in the AqH of BK patients before and after DMEK and in a control group without corneal disease." (PMID 34426617, 2021).